MAP2 (microtubule associated protein 2)
Diseases named in the same sentence as MAP2 in open-access papers (continued):
Sharing a sentence is not in itself a finding about the gene and the disease.
viral infection (4 papers, 2012 to 2024). "However, in NeuroD1-infected areas, MAP2 was partially recovered at 2 months and significantly recovered at 6 months post viral infection (NeuroD1-mCherry columns)." (PMID 33224952, 2020). "In this view, the cleavage of MAP4 and MAP2 has been characterized during viral infection." (PMID 22911759, 2012). "UNOs infected with PeV-A1 Harris or PeV-A3 152037 showed positive dsRNA (indicative of viral infection) in astrocyte (GFAP+) and neuron (MAP2+) rich areas." (PMID 38514653, 2024). "Upon examination at 12 days post‐virus infection (dpi), we observed that approximately 20% of NGN2‐expressing U251 cells underwent a dramatic morphological transformation into bipolar or multipolar elongated neuronal forms, robustly expressing TUJ1 and MAP2." (PMID 39390804, 2024).
ZIKV infection (4 papers, 2017 to 2023). "We assume that neurons perhaps have retracted their neurites due to severe ZIKV infection thereby leading to neuronal death in those weak MAP-2 stained cells." (PMID 30866785, 2019). "For example, Microtubule Associated Protein 2 (MAP2), participating in determining and stabilizing dendritic shape during neuron development, was undergone altend type of AS after ZIKV infection." (PMID 29116029, 2017). "For instance, MAP2 underwent altend, while DCC was subject to alt3 after ZIKV infection, even though the expression levels of these two genes remained the same." (PMID 29116029, 2017). "Unlike Zika virus infection, which mainly induces the apoptosis of NSCs to result in microcephaly 42, WSN primarily infects MAP2+ neurons and causes the apoptosis of both NSCs and neurons." (PMID 35910807, 2022). "In our studies with ZIKV infections, the presence of MAP-2 (neuronal marker) and absence of GFAP (astrocyte glial marker) clearly indicated the complete neuronal differentiation of progenitor cells to cortical neurons in our studies with ZIKV infections." (PMID 30866785, 2019).
amyloid (3 papers, 2013 to 2023). "Indeed, a significant amount of MAP2+ fragments was found in these microdomains of both 6m- and 12m-Tg-m, thus confirming the cytotoxic effects of amyloid plaques." (PMID 37759482, 2023). "Similar to the 5XFAD brain, BACE1 and synaptophysin displayed significant co-localization surrounding amyloid plaques, while MAP2 did not overlap with BACE1 in the AD brain." (PMID 23820808, 2013). "Consistently, the number of MAP2+/VGLUT1+ cells was significantly decreased in the AD patient iNs that expressed APOE ε4 at the amyloid-seeding stage, indicating that the conditional expression of APOE ε4 at the amyloid-seeding stage may affect the degeneration of AD patient iNs." (PMID 36284363, 2022).
brain injuries (3 papers, 2011 to 2018). "Loss of MAP2 immunostaining suggests an early vulnerability of the microtubular cytoskeleton to brain trauma." (PMID 21957448, 2011). "In our TBI study, loss of MAP2 immunostaining following CCI indicated an early vulnerability of the microtubular cytoskeleton to brain trauma not only in the contused but also to a lesser extent in the contralateral cortex (Figure 6F1–F4)." (PMID 21957448, 2011). "Other promising biomarkers have been suggested for diagnosis, monitoring and prognosis of traumatic brain injury (TBI) such as microtubule-associated protein-2 (MAP2, neuron-specific enolase (NSE), myelin basic protein (MBP), tau, s100β and neurofilament heavy chain protein (NF-H)." (PMID 30596792, 2018). "Calpain-dependent degradation of MAP2 is known as an early response to traumatic, focal ischemic brain injuries and glutamate excitotoxicity." (PMID 22272295, 2012).
cardiac arrest (3 papers, 2020 to 2025). Cessation of breathing and/or cardiac function. "Besides, post-cardiac arrest rats in the vehicle group exhibited extensive loss of MAP2-immunoreactive dendrites in the hippocampus CA1 region, which was partially recovered by Ac-YVAD-cmk treatment." (PMID 32703306, 2020). "In mouse models of cardiac arrest-induced neuronal death, tDCS enhanced expression of proteins related to synaptic function and regeneration, including MAP2, GAP43, PSD95, and synaptophysin." (PMID 41440017, 2025).
colorectal cancer (3 papers, 2017 to 2020). A primary or metastatic malignant neoplasm that affects the colon or rectum. "In contrast, the capacity of colorectal cancer stem cells to give rise to neural cells and the TH-positive cells was remarkably reduced by MAP2 knock-down." (PMID 29263908, 2017). "In addition, MAP2-dRK6 blocks growth of VEGF-secreting colorectal cancer cells in vivo by suppression of angiogenesis." (PMID 32431793, 2020).
HIV-1 infection (3 papers, 2011 to 2022). The type species of lentivirus and the etiologic agent of acquired immunodeficiency syndrome (AIDS). "HIV-1 infection causes synaptodendritic injury, and decreased SYP and MAP2 biomarkers have been associated with higher viral load and impaired cognitive function in HAND105." (PMID 35301411, 2022). "Accordingly, in order to understand the neurodegenerative role of MAP2 during HIV-1 infection and as well as during the exposure to drugs of abuse and their possible reversal by ASH, MAP2 levels were determined in cells after their exposure by Western blotting." (PMID 25415340, 2014). "MAP2 protein was down-regulated in HAND brains compared with brains from uninfected subjects, and it was partially restored in patients under treatment for HIV-1 infection." (PMID 21909266, 2011).
Huntington disease (3 papers, 2022 to 2023). Huntington disease (HD) is a rare neurodegenerative disorder of the central nervous system characterized by unwanted choreatic movements, behavioral and psychiatric disturbances and dementia. "The microtubule binding protein 2 (MAP2) was found to be altered in Huntington disease (HD) due to its alternative splicing expression mediated by SRSF6." (PMID 37904233, 2023). "In contrast, in Huntington’s Disease, MAP2 splicing is altered, leading to an imbalance between high and low molecular weight MAP2 forms that is thought to contribute to the dendritic atrophy which characterizes the disorder." (PMID 36187353, 2022). "Therefore, aberrant MAP2 splicing may represent a crucial precipitant to the structural and functional abnormalities seen in neurons affected by Huntington’s disease." (PMID 36187353, 2022).
Hypoglycemia (3 papers, 2012 to 2021). A decreased concentration of glucose in the blood. "However, pyruvate administration after R/M hypoglycemia significantly spared this loss of MAP2 intensity." (PMID 24278448, 2013). "STZ-induced diabetic rats showed significantly reduced MAP2 immunoreactivity in the cortex after RM hypoglycemia compared with pyruvate-treated diabetic rats." (PMID 24278448, 2013). "In support of these possibilities, we found that R/M hypoglycemia reduced MAP2 intensity and thickness in the stratum radiatum area of hippocampal CA1, more so in diabetic than in non-diabetic rats." (PMID 22830525, 2012). "Interestingly, we found that R/M hypoglycemia reduced MAP2 intensity even further in the parietal cortex and perirhinal cortex." (PMID 24278448, 2013). "R/M hypoglycemia in diabetic rats further decreased MAP2 fluorescent intensity." (PMID 24278448, 2013). "Here we found that R/M hypoglycemia reduced MAP2 intensity in the SR area of hippocampal CA1." (PMID 22830525, 2012).
malaria (3 papers, 2012 to 2020). Malaria is a serious and sometimes fatal disease caused by a parasite that commonly infects a certain type of mosquito which feeds on humans. "However, in P. falciparum, causing the most severe form of human malaria, PfMAP-2 was suggested to be essential for asexual proliferation indicating distinct functions for MAP-2 in these two Plasmodium species." (PMID 32681115, 2020). "We have also shown that CDC20 and MAP2 may play independent but essential roles in the mitotic division associated with microgametogenesis but are not essential for mitosis during asexual stages in the malaria parasite." (PMID 22383885, 2012).
medulloblastoma (3 papers, 2014 to 2021). A malignant, invasive embryonal neoplasm arising from the cerebellum. "For the Medulloblastoma tissue sample set, the data clearly shows overexpression of MAP2 in tumor tissue with a fold change of 1.34." (PMID 34055594, 2021). "Conversely expression of MAP2, a differentiation maker, in neural stem cells and medulloblastoma was strongly induced by JQ1." (PMID 24796395, 2014). "MAP2 is a well-known neural marker for medulloblastoma as reported in a few studies." (PMID 34055594, 2021). "The synaptic vesicle protein Synaptophysin (SYP) and the microtubule-associated protein MAP2 are both expressed in Ptch1Δ/+ medulloblastomas, but not in the cerebellar nodules of aged Ptch1Δ/+Pn-1Δ/+ mice." (PMID 25901736, 2015).
oligodendroglioma (3 papers, 2016 to 2019). A well-differentiated (WHO grade II), diffusely infiltrating neuroglial tumor, typically located in the cerebral hemispheres. "Tumor cells were positive for MAP2 with a cap-like staining pattern, characteristic of oligodendroglioma." (PMID 27806344, 2016).
ovarian carcinoma (3 papers, 2021 to 2025). A malignant neoplasm originating from the surface ovarian epithelium. "To functionally evaluate MAP2, we performed MAP2 siRNA knockdown in MAP2-high expressing, platinum-resistant ovarian cancer cell lines (OVCAR3 and OVCAR8)." (PMID 41256002, 2025). "Microtubule-stabilizing proteins (MAPs), such as tau and MAP2, may affect paclitaxel binding, but studies of its practical use in ovarian cancer are conflicting." (PMID 34944858, 2021).
pancreatic cancer (3 papers, 2022 to 2025). "Likewise, Le Large and collaborators found elevated levels of microtubule-associated protein 2 (MAP2) in GEM-resistant pancreatic cancer models that were highly sensitive to PTX both in vitro and in vivo." (PMID 35251961, 2022). "Consistent with this, IF staining for Map2 and Tuj1 in Neurog3-overexpressing cells revealed that Neurog3 upregulated the transdifferentiation of pancreatic cancer cells into cells with neuron-like phenotypes." (PMID 41225636, 2025). "High MAP2 expression correlated with paclitaxel and docetaxel sensitivity in pancreatic carcinoma cell lines." (PMID 38310601, 2024). "Furthermore, through RT-qPCR and Western Blotting experiments, we confirmed that the expression of Map2 and Tuj1 is upregulated in NeuroD1-overexpressing pancreatic cancer cells at both the gene and protein levels." (PMID 41225636, 2025). "IF staining for Map2 and Tuj1 revealed that in pancreatic cancer cells with low NeuroD1 expression, neither the control nor Neurog3-knockdown groups exhibited transition to a neuron-like phenotype, whereas Neurog3 overexpression partially induced this transition." (PMID 41225636, 2025).
pancreatic ductal adenocarcinoma (3 papers, 2000 to 2023). An infiltrating adenocarcinoma that arises from the epithelial cells of the pancreas. "We have studied the state of microtubule associated protein 2 (MAP2) in the pancreatic ductal adenocarcinomas P03 and P02 (sensitive and refractory to docetaxel respectively) since they express the corresponding mRNA and MAP2-related peptides." (PMID 10945505, 2000). "In vivo hydrolysis of MAP2 protein can increase the antitumor effect of docetaxel in pancreatic ductal adenocarcinoma." (PMID 35990843, 2022). "Studies have shown that MAP2 also expresses corresponding mRNAs and related peptides in pancreatic ductal adenocarcinoma." (PMID 35990843, 2022).
prion disease (3 papers, 2012 to 2023). A transmissible disease that is caused by a protein that is able to induce abnormal folding of normal cellular proteins, leading to characteristic spongiform brain changes, which are associated with neuronal loss without an inflammatory response. "Interestingly, the prion disease leads to cell death mediated by the alteration of the MAP2/TAU family protein; in particular, the loss of Map2 is observed in prion disease and neuronal death, followed by microtubule disruption." (PMID 37709831, 2023). "It is reasonable to speculate that the abrupt reduction of MAP2 in brain tissues is associated with the rapid increase of calpain in prion diseases." (PMID 22272295, 2012). "Recently, by screening the transcriptional diversity in the brains of human prion diseases with a commercial mRNA microarray, we found that the expression level of MAP2 is obviously decreased (unpublished data)." (PMID 22272295, 2012). "In this study we have demonstrated that levels of MAP2 in the CNS tissues of a scrapie experimental rodent model and in the postmortem brains of the patients of genetic prion diseases are significantly reduced, highlighting a common phenotype in TSEs." (PMID 22272295, 2012). "In this study, we found that MAP2 proteins in the brain tissues of scrapie agent 263K-infected rodents and human genetic prion diseases were almost undetectable at the terminal stages." (PMID 22272295, 2012). "Hence, further characterizations of the role of calpain and MAP2 in the pathogenesis of prion diseases are specially needed." (PMID 22272295, 2012).
status epilepticus (3 papers, 2016 to 2019). Status epilepticus is defined as a continuous seizure lasting more than 30 min, or two or more seizures without full recovery of consciousness between any of them. "Upf1 also co-localized with Map2, a marker of dendrites, in the hippocampus after status epilepticus, particularly around area CA2." (PMID 28128343, 2017). "To determine whether status epilepticus drives changes in Upf1 localization we double-stained brain sections with specific antibodies against Upf1 and either the axonal marker AnkyrinB or the dendritic marker Map2." (PMID 28128343, 2017). "Recent studies have reported prominent microgliosis overlapped with decreased MAP2 immunoreactivity and phosphorylation in CA1 stratum radiatum area at 2 and 3 weeks after status epilepticus." (PMID 31416451, 2019).
embryonal carcinoma (2 papers, 2015 to 2022). A non-seminomatous malignant germ cell tumor characterized by the presence of large germ cells with abundant cytoplasm resembling epithelial cells, geographic necrosis, high mitotic activity, and pseudoglandular and pseudopapillary structures formation. "As previously shown, the P19 embryonal carcinoma cell line that stably expresses Myc-CDC42 but not Myc-CDC42b failed to become neurons and upregulate the expression of MAP2 in RA-induced neuronal differentiation." (PMID 36206843, 2022).
encephalitis (2 papers, 2019 to 2023). An acute inflammatory process affecting the brain parenchyma. "Therefore, neuron-specific nuclear protein (NeuN) was used as a specific neuronal marker to assess neuronal loss in anti-NMDAR encephalitis mice and the effect of PI3K inhibition on it, whereas microtubule-associated protein 2 (MAP2) was used to detect neuronal plasticity in brain tissue." (PMID 37314618, 2023).
Hirschsprung disease (2 papers, 2025 to 2026). Hirschsprung disease (HSCR) is a congenital intestinal motility disorder that is characterized by signs of intestinal obstruction due to the presence of an aganglionic segment of variable extent in the terminal part of the colon. "It has demonstrated efficacy as an immunohistochemical biomarker of submucosal ganglion cells, particularly useful in the exclusion of Hirschsprung disease (HSCR) by detecting ganglion cells and nerve fibrils more efficiently than biomarkers as MAP‐2 and Calretinine." (PMID 39995075, 2025).
infarct (2 papers, 2018 to 2019). "The rehabilitation performance was subsequently rated using an incline test, a rotarod test, the infarction volume, the lesion volume, the number of MAP2 positive cells and the level of cortisol." (PMID 31603928, 2019).
lupus (2 papers, 2022 to 2025). "Notably, in addition to increased PSD accumulation, C1q also colocalized in cells with neuronal morphology and MAP2-positive neurites in the lupus brain." (PMID 35177587, 2022).
neuroendocrine tumor (2 papers, 2013 to 2024). "Tumorspheres derived from pRb-negative tumors do not express pRb and express the neuroendocrine tumor markers synaptophysin and microtubule-associated protein 2 (MAP2)." (PMID 23826078, 2013).
neuroepithelial neoplasm (2 papers, 2021 to 2024). A neoplasm of the nervous system that arises from the neuroepithelial tissues. "It has been shown that MAP2 is a valuable diagnostic tool to recognize and diagnose low-grade neuroepithelial neoplasms." (PMID 34660263, 2021). "Scattered neurons, identified by neuronal nuclei antigen and microtubule-associated protein-2 staining, were consistently observed in all dysembryoplastic neuroepithelial tumours and myxoid glioneuronal tumours examined, but only in one rosette-forming glioneuronal tumour." (PMID 38764775, 2024).
peripheral nerve injuries (2 papers, 2021 to 2022). "There is a possibility that oleic acid could offer some neurotrophic benefit in peripheral nerve injuries, similar to axonal development in brain tissue via increasing expression of axonal growth-associated protein and microtubule-associated protein-2." (PMID 34768986, 2021).
prostate carcinoma (2 papers, 2023 to 2024). A carcinoma that arises from epithelial cells of the prostate gland. "Investigation of Microtubuli-associated Protein 2 (MAP2) expression and its clinical relevance in prostate cancer." (PMID 38310601, 2024). "For example, fostamatinib, targeting PIK3C2B, has been used for the treatment of chronic immune thrombocytopenia; and estramustine, targeting MAP2, has been used for prostate cancer." (PMID 38102678, 2023). "Additionally, MAP2 protein expression was quantitatively analysed in the serum of histologically confirmed prostate carcinoma patients and the control group using a commercial enzyme-linked immunosorbent assay." (PMID 38310601, 2024). "In summary, we hypothesize that MAP2 might be a candidate biomarker for an improved prognostic evaluation of prostate cancer specimens." (PMID 38310601, 2024).
vascular dementia (2 papers, 2022 to 2025). A degenerative vascular disorder affecting the brain. "A recent study reported ROCK 1/2, and inflammatory cytokines (IL-1 and IL-6) were upregulated in vascular dementia models while the expression of claudin-5, which maintains the blood–brain barrier, and MAP2 as a nerve cell-specific factor, were decreased in the hippocampal region." (PMID 39779619, 2025). "However, expression of claudin-5, which maintains the blood–brain barrier, and MAP2 as a nerve cell-specific factor, was decreased in the hippocampal region of the vascular dementia model." (PMID 35203655, 2022).
age-related macular degeneration (1 paper, 2021). Age-related loss of vision in the central portion of the retina (macula), secondary to retinal degeneration. "In donor retinae of patients with age-related macular degeneration, MAP-2 labelling was noted in the inner segments of abnormal photoreceptors with abnormally located nuclei." (PMID 35053014, 2021).
Aphasia (1 paper, 2020). An acquired language impairment of some or all of the abilities to produce or comprehend speech and to read or write. "Secondary outcomes: traditional Chinese medicine (TCM) syndrome score scale; western aphasia battery (WAB); water swallow test; Montreal cognitive assessment (MoCA); growth-associated protein-43 (GAP-43); microtubule-associated protein-2 (MAP-2)." (PMID 32358398, 2020).
Atrophy (1 paper, 2008). Any weakening or degeneration, especially through lack of use. "Since NF-H, MAP2 and myelin basic protein (MBP) are substrates of calpain, and calpain is known to be involved in Aβ-induced axonal atrophy, expression levels of calpain and calpastatin were measured." (PMID 18706097, 2008).